FOXP3 (forkhead box P3)
Diseases named in the same sentence as FOXP3 in open-access papers (continued):
Sharing a sentence is not in itself a finding about the gene and the disease.
cerebral artery occlusion (1 paper, 2012). "By using a mouse model of selective FoxP3+ Treg ablation they could even identify Treg as key mediators of ischemic neurodegeneration – at least during the early phase after transient middle cerebral artery occlusion." (PMID 22883324, 2012).
cerebrovascular diseases (1 paper, 2024). "Additionally, the review covers the roles of ICPs in modulating CD4+Foxp3+ regulatory T cells (Tregs), T cells, and innate immune cells in various CVDs and cerebrovascular diseases." (PMID 39926714, 2024).
Chlamydia infection (1 paper, 2013). "Thus, Chlamydia infection of the reproductive tract induces a heterogenous T helper response that comprises expanded T-bet+ Th1 cells, T-bet+Foxp3+ Tregs, and Th17 cells that are enriched in infected non-lymphoid tissues." (PMID 24204262, 2013).
chlamydial infection (1 paper, 2019). "This emphasizes the cross talk between ECC1 cells and the PBMCs when cultured together, in which TGF-β1 and FoxP3 switched to upregulated expression levels upon chlamydial infection." (PMID 30832593, 2019).
cholestasis (1 paper, 2024). Impairment of the bile flow caused by obstruction within the liver, or outside the liver in the bile duct system. "A biliary stricture gene signature, reflecting cholestasis, was mildly upregulated in ALGS samples, while both immature T cell and Treg (FOXP3-driven) gene signatures were significantly enriched in livers from patients with ALGS (Fig. EV5G)." (PMID 39358604, 2024).
Cholestatic liver disease (1 paper, 2021). "In an animal model of cholestatic liver disease, infiltration of CD8+ T-cells was enhanced by depletion of Foxp3+ Treg cells." (PMID 34440196, 2021).
chronic allograft nephropathy (1 paper, 2022). "In a study of urinary Foxp3 mRNA and other T cell markers at the time of renal biopsy, the mean ratio of Foxp3 mRNA to 18S ribosomal RNA copies is higher in urine from RT patients with acute rejection (n=36) than those with chronic allograft nephropathy (n=18) or normal biopsies (n=29)." (PMID 36426347, 2022).
chronic endometritis (1 paper, 2022). A non-granulomatous or granulomatous chronic inflammation of the endometrium. "A study on chronic endometritis has shown abundant immune cells in the endometrium and an increase in CD83+ mature DCs, CD68+ macrophages, CD8+ T cells, and Foxp3+ Treg cells; these results might be reasonable for impaired endometrial receptivity and recurrent pregnancy failures." (PMID 36686483, 2022).
chronic liver failure (1 paper, 2011). Liver failure that develops slowly and gradually for some time, possibly for years, often as the result of cirrhosis, or malnutrition. "To this end, we analyzed the expression patterns of Foxp3- and IL-23/IL-17 pathway-related proinflammatory cytokines in 39 patients with acute-on-chronic liver failure, 71 patients with CHB and 32 healthy controls." (PMID 21489307, 2011).
chronic nasopharyngitis (1 paper, 2020). "We found a substantial population of Foxp3+ Tregs in NPC tissues (106.7 ± 57.0) and a small amount in chronic nasopharyngitis (39.3 ± 23.6)." (PMID 32573058, 2020).
chronic osteomyelitis (1 paper, 2022). "Previous studies have reported that STAT5/CD4+CD25+FOXP3 Tregs pathway plays a critical role in the pathogenesis of chronic osteomyelitis and acute ischemic stroke." (PMID 36162982, 2022).
chronic pancreatitis (1 paper, 2022). A chronic inflammatory process causing damage and fibrosis of the pancreatic parenchyma. "Here, we investigated the effect of FOXP3+CD25+ Treg cells in a mouse model of chronic pancreatitis using DEREG mice that were depleted of regulatory T cells." (PMID 35922425, 2022).
chronic tonsillitis (1 paper, 2015). "Because Foxp3 and CD25 are antigens that identify Treg cells, a greater number of these cells are thought to infiltrate the lymphatic tissue of the palatine tonsils in chronic tonsillitis, i.e., under conditions of chronic inflammation." (PMID 25773455, 2015).
CNS demyelinating diseases (1 paper, 2024). "Alternatively, the polysaccharide A of Bacteroides fragilis can directly induce differentiation of naïve CD4+ T cells to IL-10 producing FoxP3 + Treg cells, thereby conferring protection against CNS demyelinating diseases." (PMID 38352704, 2024).
colonic disease (1 paper, 2023). "Mice with conditional ablation of IL-10 in Foxp3+ Tregs (IL-10cKO) are largely spared from the severe colonic disease that global IL-10KO mice develop (Ref." (PMID 37314833, 2023).
contact dermatitis (1 paper, 2025). An inflammatory skin condition caused by direct contact between the skin and either an irritating substance or an allergen. "PIP binds to CD4 and inhibits the CD4-HLA-DR interaction, induces differentiation of naive T cells into CD4(+) CD25(+) forkhead box P3(+) (FOXP3(+)) Treg cells, and exerts both local and systemic immunosuppressive effects in mouse contact dermatitis." (PMID 39938773, 2025).
cryptococcal infection (1 paper, 2025). "For example, in a Cryptococcus neoformans infection model, conditional depletion of Foxp3+ Tregs resulted in elevated pulmonary Th2 cell counts, indicating that Tregs restrict the expansion of Th2 cells induced by cryptococcal infection." (PMID 40806563, 2025).
cutaneous T-cell lymphoma (1 paper, 2020). "In addition, scRNA-seq analysis has observed FOXP3 + malignant T cells and GATA3 + or IKZF2 +(HELIOS)tumor cells that are transformed from FOXP3 + T cells during cloning and evolution of Sézary, an aggressive form of cutaneous T-cell lymphoma." (PMID 33614479, 2020).
diabetic neuropathy (1 paper, 2017). A chronic, pathological complication associated with diabetes mellitus, where nerve damages are incurred due to diabetic microvascular injury involving small blood vessels that supply these nerves, resulting in peripheral and/or autonomic nerve dysfunction. "In contrast to diabetic neuropathy, Treg numbers as defined by CD127 (CD4+CD25highCD127low) and/or FoxP3 markers (CD4+CD25highFoxP3+ or CD4+CD25highCD127lowFoxP3+) were inversely correlated with HDL cholesterol and ApoAI." (PMID 28553653, 2017).
diabetic retinopathy (1 paper, 2025). "Inflammation contributes to the development of diabetic retinopathy, but little is known about the role of the adaptive immune system, including the benefits of augmenting the Forkhead box protein P3 (Foxp3) regulatory T cell (Treg) compartment." (PMID 40133487, 2025).
disseminated candidiasis (1 paper, 2014). Systemic candidiasis occurs when Candida yeast enters the bloodstream and may spread (becoming disseminated candidiasis) to other organs, including the central nervous system, kidneys, liver, bones, muscles, joints, spleen, or eyes. "In disseminated candidiasis, the role of Foxp3+ regulatory T (Treg) cells remains largely unexplored." (PMID 24435677, 2014). "The in vivo expansion of Foxp3+ T cells in the model of disseminated candidiasis correlates positively (p = 0.006, Rs = 0.779) with kidney fungal burden, suggesting that T cells with a Treg-cell phenotype may be associated with the progression of infection." (PMID 24435677, 2014). "Our data suggest a model whereby pathology results from excessive Th17-cell responses associated with Foxp3 induction in disseminated candidiasis, while not excluding a role for lower levels of IL-17A in protection from the fungus." (PMID 24435677, 2014).
diverticulitis (1 paper, 2019). An infection that develops in the diverticula of the intestinal tract. "Although FOXP3+ Treg accumulation in the inflamed mucosa of IBD has been observed in some studies, such an increase was not as apparent as in other intestinal inflammatory diseases, such as diverticulitis." (PMID 30918515, 2019).
Duchenne muscular dystrophy (1 paper, 2014). Duchenne muscular dystrophy (DMD) is a neuromuscular disease characterized by rapidly progressive muscle weakness and wasting due to degeneration of skeletal, smooth and cardiac muscle. "Both in JDM and Duchenne’s muscular dystrophy the proportion of FOXP3+ T cells in muscles were increased compared to JDM peripheral blood." (PMID 25157414, 2014).
ductal carcinoma in situ (1 paper, 2017). "This idea is supported by a study showing that higher ratios of FOXP3+CD4+ to CD8+ T cells in biopsies from BC patients with ductal carcinoma in situ predict their relapse." (PMID 29163490, 2017).
duodenitis (1 paper, 2019). Acute or chronic inflammation of the duodenum. "Tregs cells in the intestines (FoxP3+ expressing cells) were increased in patients with SS/HTLV-1 compared with patients with chronic duodenitis (SS/HTLV-1: 1.5 [IQR: 0.7–2.3]; duodenitis controls: 0 [range 0–0.7]; healthy controls: 0; Mann-Whitney p = 0.034)." (PMID 31170141, 2019).
embryonal carcinoma (1 paper, 2024). A non-seminomatous malignant germ cell tumor characterized by the presence of large germ cells with abundant cytoplasm resembling epithelial cells, geographic necrosis, high mitotic activity, and pseudoglandular and pseudopapillary structures formation. "Higher numbers were also detected in embryonal carcinoma and mixed tumors, although not statistically significant different when compared to contralateral, tumor-free testes, which also contain small numbers of CD25 + FOXP3+ Treg cells." (PMID 38649788, 2024).
empyema (1 paper, 2021). An accumulation of pus in a body cavity, usually the pleural space. "The diagnostic accuracy of CD4+IL-9+, CD4+IL-17+, CD4+IL-22+, CD4+CD25+FOXP3+ T cells, and ADA in the differentiation of tuberculous from non-tuberculous effusions (malignant, empyema, and parapneumonic effusions)." (PMID 34925358, 2021).
End Stage Liver Disease (1 paper, 2011). Final stage of a liver disease when the liver failure is irreversible and LIVER TRANSPLANTATION is needed. "Our finding that Foxp3+ T cells in the ACLF and CLF patients were similar is in contrast to that study, probably because the patients enrolled in our study suffered from severe and end-stage liver diseases." (PMID 21851644, 2011).
endometrioid tumor (1 paper, 2024). A benign, borderline, or malignant epithelial tumor of the female reproductive system characterized by the presence of glands and/or cysts lined by neoplastic cells that resemble endometrial cells. "In contrast, endometrioid tumors were indicated to have a stronger presence of Tregs (FOXP3 and CTLA-4), and tumor PD-L1 and IDO1 levels on par with HGSC." (PMID 39026018, 2024).
epidermolysis bullosa acquisita (1 paper, 2024). "More recent experimental evidence in a mouse model of epidermolysis bullosa acquisita would confirm the immunomodulatory role of vitamin D via increase of CD4+ forkhead box P3 (FoxP3)+ Tregs and B cells (CD19 + IL10+), concomitant with the reduction of proinflammatory Th17 cells." (PMID 39796035, 2024).
epithelioid mesothelioma (1 paper, 2017). "In summary, our data demonstrate for the first time an association of survival with high CD4+, low FOXP3+, high CD20+, low NP57+ and low CD68+ counts in epithelioid mesothelioma, treated with palliative intent." (PMID 28817839, 2017).
esophageal tumors (1 paper, 2017). "In esophageal tumors, high FoxP3+ density was significantly associated with a prolonged OS in univariable but not in multivariable Cox regression analysis." (PMID 29069772, 2017).
Follicular Cyst (1 paper, 2024). Cyst due to the occlusion of the duct of a follicle or small gland. "Four cows that developed follicular cysts were homozygous for the G allele of the FOXP3 gene related to repeat breeders." (PMID 38791678, 2024). "Despite the limited number of animals examined, we demonstrated a significant positive correlation between postpartum PAG and SAA concentrations, the possibility of postpartum PAG variation, FOXP3 allele variation, and the occurrence of follicular cysts." (PMID 38791678, 2024). "A change in PAG concentration will be related to inflammatory parameters, such as SAA and MAA, FOXP3 variants, subsequent postpartum clinical diseases (mastitis, ketosis, and follicular cysts), and reproductive performance (days open) during the postpartum period." (PMID 38791678, 2024). "Furthermore, some aspects of decreased postpartum PAG concentration may suggest a relationship between the development of follicular cysts and the FOXP3 variant." (PMID 38791678, 2024). "Furthermore, some aspects of postpartum uterine recovery may be associated with the development of follicular cysts and FOXP3 variants." (PMID 38791678, 2024). "PAG concentration was correlated with inflammatory parameters (serum amyloid A and milk amyloid A), postpartum inflammatory conditions (mastitis, ketosis, and follicular cysts), and FOXP3 gene-related repeat breeders." (PMID 38791678, 2024). "We evaluated the relationship between decreased pregnancy-associated glycoprotein (PAG) levels, inflammatory parameters (serum amyloid A [SAA] and milk amyloid A [MAA]), postpartum inflammatory conditions (mastitis, ketosis, and follicular cysts), and the FOXP3 gene." (PMID 38791678, 2024). "However, this study presents basic information, and the researcher may conduct a future study about the relationship between FOXP3 and follicular cysts." (PMID 38791678, 2024).
gallbladder adenocarcinoma (1 paper, 2021). A carcinoma that arises from glandular epithelial cells of the gall bladder. "To validate the scRNA‐seq results, we analyzed independent gallbladder adenocarcinoma and adjacent normal tissues by immunohistochemistry (IHC) staining and found a significant increase of FOXP3+ or CD4+ cells and a reduction of CD8A+ cells in tumors." (PMID 34185421, 2021).
gastric diseases (1 paper, 2017). "Other normal tissues and gastric disease tissues, which exhibited relatively high expression of CD8/Foxp3 and CD8/PD-L1, were clustered into another group (sample 24, normal gastric mucosa tissue), and two normal adjacent tissues comprised the third group." (PMID 29025424, 2017). "Other normal tissues and gastric disease tissues, which exhibited relatively high expression of CD8/Foxp3 and CD8/PD-L1, were clustered into another group." (PMID 29025424, 2017).
gastric neuroendocrine tumors (1 paper, 2021). "The purpose of this study was to characterize the densities of CD3+, CD8+, CD4+ and FOXP3+ T cells in small bowel neuroendocrine tumors (SB-NETs), SB-NET lymph node metastases and gastric neuroendocrine tumors (G-NETs) to assess the prognostic role of immune cell infiltrates in SB-NETs." (PMID 34208144, 2021).
giardiasis (1 paper, 2024). An infection of the small intestine caused by the flagellated protozoan giardia lamblia. "A study with cattle infected with G. lamblia showed that the proliferation of TCD4+FOXP3- cells occurs, suggesting the existence of regulatory mechanisms during giardiasis that may contribute to the parasite’s evasion in the face of immune responses." (PMID 39062459, 2024).
glomerulopathies (1 paper, 2021). "Although it is universally accepted that FOXP3+ Tregs biological action aims at suppressing the immune response, the association between the FOXP3+ Tregs immunohistochemical expression and standard histological lesions seems to be controversial in primary as well as in secondary glomerulopathies." (PMID 34336285, 2021). "Data about FOXP3+ Tregs' presence and role in primary glomerulopathies of native kidneys are minimal." (PMID 34336285, 2021). "This is a comparative study on FOXP3+ Tregs renal tissue expression in human adults with the primary glomerulopathies IgAN, FSGS, and MGN." (PMID 34336285, 2021). "FOXP3+ Tregs intrarenal infiltration in primary glomerulopathies is common." (PMID 34336285, 2021). "Thus, given the heterogeneity of our patient cohort regarding renal function level, we consider that FOXP3+ Tregs recruitment in renal tissue may occur early in the pathogenesis of glomerulopathies before the establishment of severe histological lesions." (PMID 34336285, 2021). "No statistical difference was found between the three glomerulopathies in the absolute count of FOXP3+ Tregs in the interstitial tissue per mm2 and FOXP3+ Tregs over CD4+ and CD3+ ratios." (PMID 34336285, 2021).
glomerulosclerosis (1 paper, 2021). A hardening of the kidney glomerulus caused by scarring of the blood vessels. "In patients with global glomerulosclerosis, interstitial fibrosis ≥25%, or dense interstitial inflammation, FOXP3+ Tregs count in the interstitial tissue was not significantly different." (PMID 34336285, 2021).
granulomatosis with polyangiitis (1 paper, 2019). A small-vessel necrotizing vasculitis characterized by the association of inflammation of the vessel wall and peri- and extravascular granulomatosis. "Previous studies in Granulomatosis with Polyangiitis (GPA-)patients have demonstrated an increase in FoxP3+T-cells with impaired suppressive capacity and an increase in Th17 cells." (PMID 31164680, 2019).
hematoma (1 paper, 2019). A hematoma is a collection of blood from a vascular structure into an extravascular space. "FoxP3+ Tregs are gradually activated in the border of CSDH, and the increase in Treg number is closely associated with higher hematoma absorption rates during atorvastatin treatment." (PMID 31595197, 2019). "Furthermore, FoxP3+ Tregs were mainly localized in the vicinity of the intracranial lesions of hematoma, such as on the dura and the neomembrane between the hematoma and cortex surface." (PMID 31595197, 2019).
hemophilia B (1 paper, 2020). Hemophilia B is a form of hemophilia characterized by spontaneous or prolonged hemorrhages due to factor IX deficiency. "Next, we examined the relative frequencies of FoxP3+ and LAP+ Treg in the immune system lining the small and large intestines in hemophilia B mice upon completion of our oral tolerance regimen." (PMID 32508814, 2020). "Further analyses of Treg CD4+ lymphocyte sub-populations in hemophilia B mice reveal a marked increase in the frequency of CD4+CD25−FoxP3−LAP+ T cells (but not of CD4+CD25+FoxP3+ T cells) in the lamina propria of the small but not large intestine." (PMID 32508814, 2020).
hemorrhagic stroke (1 paper, 2013). A stroke caused by a bleed on the brain. "Furthermore, since current Treg research mainly concentrated on ischemic rather than hemorrhagic stroke, future studies should broaden their knowledge of FoxP3+CD25+CD4+ Tregs in hemorrhagic stroke, including subarachnoid hemorrhage, intracerebral hemorrhage, and hemorrhagic transformation." (PMID 23983771, 2013).
hepatic granuloma (1 paper, 2012). A granuloma located in the liver. "Immunohistochemical analysis demonstrated the presence of Foxp3+ T cells in L. donovani–induced hepatic granulomas and perivascular neo-lymphoid aggregates." (PMID 22928057, 2012).
hilar cholangiocarcinoma (1 paper, 2022). A cholangiocarcinoma that arises from the junction, or adjacent to the junction, of the right and left hepatic ducts. "Forkhead box M1 bound to the FoxP3 promoter region to promote FoxP3 transcription and recruit FoxP3+ Treg cells, thereby inducing Hilar cholangiocarcinoma immune escape." (PMID 36301031, 2022).